CCL5 (C-C motif chemokine ligand 5)
Diseases named in the same sentence as CCL5 in open-access papers (continued):
Sharing a sentence is not in itself a finding about the gene and the disease.
breast cancer (continued). "Herein, we provide the first evidence of CCL5-inducible signalling events in breast cancer cells, mediated by CCR5, that regulate metabolic activity to support enhanced cell proliferation, migration and invasion facilitating tumour progression." (PMID 27335323, 2016). "In an earlier publication, we provided evidence that CCL5 treatment promotes the proliferation of MCF-7 human breast cancer cells, through mTOR-dependent mRNA translation of a subset of proteins associated with cell cycle progression and survival." (PMID 27335323, 2016). "In the context of breast cancer, chemokines have been implicated in promoting the malignant phenotype: CXCL3, CXCL12, CXCL13, CCL21 and CCL5 are associated with tumour progression and metastasis in breast cancer." (PMID 27335323, 2016). "This has implied that signaling through CCL5/CCR5 is needed for tumor vascularisation in breast cancer." (PMID 27863423, 2016). "We have shown increased phosphorylation of Y705F-STAT3 in the MSC pretreated with cisplatin, and also increased expression of CCL5 in breast cancer cells cultivated in CM from pretreated MSC." (PMID 26759169, 2016). "Breast cancer cells are thought to provoke CCL5 secretion by MSCs, which increases their own motility, invasion and metastatic potential." (PMID 27275004, 2016). "These chemokines are also known to regulate the expression of the pro-inflammatory cytokines MCP-1 (monocyte chemotactic protein-1; CCL2), IL-8 (CXCL8), and RANTES (CCL5) in breast cancer." (PMID 27515302, 2016). "Mesenchymal stem cells (MSC) also play a role in breast cancer metastasis through secretion of CCL5." (PMID 27136535, 2016). "Consistent with our earlier data, in a 5 day time course study, we show that CCL5 treatment increases the proliferation of the three breast cancer cell lines." (PMID 27335323, 2016). "A very recent study in breast cancer cells demonstrated that CCL5 increases glucose uptake and that CCL5-CCR5 interactions can increase cell anabolic metabolism, specially glycolysis, using metabolomic analysis." (PMID 27898058, 2016). "Next, we examined the effects of CCL5 treatment on the migration/chemotaxis and invasive capacity of the different breast cancer cell types." (PMID 27335323, 2016). "In this report, we provide evidence that CCL5 enhances the proliferation of human breast cancer cell lines (MDA-MB-231, MCF-7) and mouse mammary tumour cells (MMTV-PyMT), mediated by CCR5 activation." (PMID 27335323, 2016). "Overexpression of the IRX2 transcription factor in BT-549 and Hs578T breast cancer cells leads to concordant repression of CCL5, CXCL8 and CXCL10 mRNA expression." (PMID 26560478, 2015). "For instance the expression of the chemokine CCL5 (RANTES) can be correlated with progressive disease in breast cancer and bone metastasis of breast cancer cells is depending on signaling through the associated receptor CCR5." (PMID 26560478, 2015). "We show that RKIP regulates in vitro breast cancer cell invasion by modulating the expression level of CCL5." (PMID 26375811, 2015). "Breast cancer cells stimulate CCL5 secretion by MSCs, and CCL5 in turn mediates MSC-induced cancer cell migration and invasion." (PMID 25483835, 2015). "From the study, we found that IL6 and CCL5 are overexpressed in basal breast cancer, suggesting their potential as therapeutic targets." (PMID 26173622, 2015). "Using a combination of loss- and gain-of-function approaches, we show that RKIP hinders breast cancer cell invasion by inhibiting expression of the CC chemokine CCL5 in vitro." (PMID 26375811, 2015). "Future prospective studies are required to establish the link between CCL5 expression, metastatic potential, and survival in breast cancer subtypes." (PMID 26173622, 2015). "IL6 and CCL5 gene expression are basal breast cancer specific, whereas high gene expression of GP130 was observed in luminal A/B." (PMID 26173622, 2015).
breast cancer (continued). "It is therefore possible that RKIP regulates the expression of CCL5 by a similar mechanism in breast cancer cells." (PMID 26375811, 2015). "Similar analyses have shown that the release of CCL5 by cells of the tumor microenvironment promotes the metastatic spread to the liver of breast cancer cells." (PMID 25885919, 2015). "Among them, the CC chemokines RANTE/CCL5 is as one of the key chemotactic factors for macrophages in breast cancer." (PMID 26375811, 2015). "Of the many chemokines, we chose to investigate the role of RKIP in the regulation of CCL5 expression owing to its involvement in breast cancer development and progression." (PMID 26375811, 2015). "It was shown that tumor cell-derived CCL5 promoted breast cancer by recruiting macrophages into the tumor microenvironment." (PMID 26375811, 2015). "We also show that the expression levels of RKIP and CCL5 are inversely correlated among clinical human breast cancer samples." (PMID 26375811, 2015). "We observed that in established human and mouse breast cancer cell lines the expression level of CCL5 was negatively regulated by RKIP." (PMID 26375811, 2015). "Knocking down RKIP expression in high-RKIP-expressing breast cancer cells boosts CCL5 expression and increases cell invasion." (PMID 26375811, 2015). "Similar to CSF2, chemokine CCL5 is significantly overexpressed in basal over luminal breast cancer in both TCGA (p-value of 9 × 10−8) and METABRIC (p-value below 2 × 10−16)." (PMID 26173622, 2015). "Taken together, it is possible that RKIP inhibits breast cancer metastasis by interfering with the macrophage recruitment by shutting down CCL5 expression by the cancer cells." (PMID 26375811, 2015). "Once recruited to the TME, stromal MSCs secrete CCL5 (RANTES) and enhance the metastatic capability of breast cancer cells." (PMID 26075202, 2015). "It was documented that the autocrine activities of CCL5 promoted breast cancer cells invasion in vitro." (PMID 26375811, 2015). "CCL5 is also significantly overexpressed in HER2+ breast cancer relative to luminal in METABRIC (p-value of 9 × 10−9) with a similar trend that failed to reach statistical significance in TCGA (p-value of 0.09)." (PMID 26173622, 2015). "The CCL5/CCR5 (CCL5 receptor) axis is active in patients affected by aggressive basal subtype of breast cancer." (PMID 24591761, 2014). "Recently, ovarian CSCs have been reported to release CCL5 into the culture medium, a chemokine known to play a role in breast cancer metastasis and whose secretion can be triggered by co-culturing breast cancer cells with mesenchymal stem cells." (PMID 24728412, 2014). "CCL5 serum levels are elevated in breast cancer patients compared to healthy individuals and tend to be higher in lymph-node-positive patients, larger tumor size, the presence of lymphovascular invasion and multifocal tumors." (PMID 24523569, 2014). "For instance, breast cancer cells induce MSCs de novo CCL5 (RANTES) secretion which then acts as a paracrine mediator of increased motility, invasion and metastatic abilities of the tumor cells." (PMID 25303976, 2014). "MSCs-derived CCL5 promotes mammary tumor cell invasion and the activation of matrix metalloproteinases (MMPs), consistent with the fact that CCL5 is capable of upregulating the release of MMP-9." (PMID 24523569, 2014). "A chemokine receptor antagonist of the CCL5 receptors, CCR5 and CCR1, was shown to inhibit experimental breast tumor growth, further implicating CCL5 as an important molecule in breast cancer." (PMID 24591756, 2014). "Tat can up-regulate cytokines (i.e., IL-6, IL-8) expression in breast cancer cells, and can also increase the expression of the chemokine CCL5 in astrocytes." (PMID 26784879, 2014). "MSCs are recruited by developing breast tumors where they can enhance the metastatic potential of weakly tumorigenic breast cancer cells through the secretion of CCL5." (PMID 24523569, 2014).
breast cancer (continued). "Human adipose-derived stem cells represent a cellular source of CCL5 which influences tumor cell migration and invasion of human breast cancer cell line MDA MB 231 in paracrine and autocrine fashion." (PMID 24591756, 2014). "A functional CCR5 receptor is expressed by a subpopulation of human breast cancer cell lines and displays a functional response to CCL5." (PMID 24523569, 2014). "Some studies have shown that CCL2 and CCL5 expressions are higher in breast cancer tissue than in corresponding normal tissue." (PMID 24591761, 2014). "CCL5, together with tumor-derived colony-stimulating factors, promotes mammary tumor progression generating MDSCs in the bone marrow, helping to maintain the immunosuppressive capacity of human MDSCs." (PMID 24523569, 2014). "CCL5 also concurs with the cross-talk between breast cancer cells and MSCs: cancer cells stimulate CCL5 secretion by MSCs and osteoblasts of the tumor microenvironment and CCL5 in turn induces tumor cell migration and promotes invasion and metastasis." (PMID 24523569, 2014). "It is evident that CCL2 (MCP-1), CCL5 (RANTES), and CXCL8 (IL-8) have pro-malignant activity that is associated with breast cancer progression and more advanced disease." (PMID 24260134, 2013). "Breast cancer cells stimulated de novo secretion of the chemokine CCL5 (also called RANTES) from MSC, which then acted in a paracrine fashion on cancer cells to enhance their motility, invasion and metastasis." (PMID 24348516, 2013). "CCL5 activation stimulates the growth of MCF-7 breast cancer cells through an mTOR-dependent mechanism." (PMID 23946783, 2013). "Mesenchymal stromal cells enhance tumor metastasis in breast carcinoma models implicating the role of pro-angiogenic CCL5." (PMID 22844466, 2012). "The inflammatory chemokines CCL2 (MCP-1) & CCL5 (RANTES) and the inflammatory cytokines TNFα & IL-1β were shown to contribute to breast cancer development and metastasis." (PMID 21486440, 2011). "In this study, we asked if associations exist between the inflammatory chemokines CCL2 & CCL5 and the inflammatory cytokines TNFα & IL-1β in breast cancer." (PMID 21486440, 2011). "To determine if this indeed the case, we have initiated this study by determining the expression patterns of CCL2, CCL5, TNFα and IL-1β in biopsy sections of healthy individuals and in breast cancer patients at different progression stages of disease." (PMID 21486440, 2011). "A similar effect, whereby direct cell-cell contact between breast cancer cells and mesenchymal stem cells induced secretion of CCL5 by the latter cells has been reported previously." (PMID 20637104, 2010). "CXCR4 is known to be upregulated in breast tumors; neutralizing the interaction of CXCL12 with CXCR4 significantly reduces breast cancer cell metastases in vivo, as does the repression of CCL5 that has anti-migratory effects." (PMID 19123925, 2009). "For instance, mesenchymal stem cells in the tumor stroma are able to increase breast cancer cell motility through paracrine CCL5 signaling." (PMID 18611264, 2008). "Similarly, mammary tumor cells with reduced Ccl5 expression attenuated lung metastasis whereas Ccl5 overexpression increased TAMs and rescued metastasis." (PMID 39566333, 2025). "CCL5 decreases breast cancer cell responsiveness to epirubicin." (PMID 40076892, 2025). "Notably, levels of CCL2 and CCL5 are significantly elevated in the blood of breast cancer patients, particularly those with ER-positive tumors, and positively correlate with TAM infiltration." (PMID 40909271, 2025). "Additionally, HSF1 seems to prevent CD8 + T-cell recruitment to breast cancer microenvironment by downregulating the expression of CCL5." (PMID 40287736, 2025). "Similarly, it has been indicated that CCL5 plays a significant chemotactic role in recruiting Treg cells in breast cancer and PDAC." (PMID 39143228, 2025). "Upregulation of CCL5 has been reported to increase the invasive potential of breast cancer cells." (PMID 40118451, 2025).
breast cancer (continued). "Moreover, CCL5 enhances breast cancer migration and invasion accompanied by increased vimentin and decreased e-cadherin expression." (PMID 40076892, 2025). "CCL5 was highly expressed in white adipose tissue and may promote breast cancer development through inflammation and immune pathways." (PMID 38676834, 2024). "We found that DHEA completely abrogated the secretion of CCL5 by breast cancer cells, suggesting that this cytokine may mediate the anti-tumoral properties of DHEA in TNBC cell lines." (PMID 36765778, 2023). "In biopsies from breast cancer patients, the local CCL5 protein expression was observed to be elevated in invasive breast carcinomas compared to in situ ductal tumors or benign lesions, and CCL5 expression was immunolocalized in biopsies specifically representing the tumor–stroma border." (PMID 37444610, 2023). "Given that the CCR5/CCL5 axis regulates DNA damage repair and breast cancer stem cell expansion, it remains to be tested whether RUNX dysregulation can elicit DNA damage in cancer stem cells through the transcriptional regulation of CCL5." (PMID 37190015, 2023). "Interestingly, we found that the addition of CCL5 recombinant protein in the conditioned media of breast cancer cells treated with DHEA rescued monocyte recruitment and, in an autocrine manner, TNBC cell migration." (PMID 36765778, 2023). "In addition, breast cancers (BRCA) with high expression of CCL5 and TNFSF15 and ovarian cancers (OV) with high expression of CXCL10 exhibited better prognoses." (PMID 37980406, 2023). "Future investigations, e.g., using gene silencing, may further validate the impact of the CCL5/CCR1 interaction on breast cancer progression in a 3D adipose microenvironment." (PMID 37444610, 2023). "Hypoxia also activates CCR5 and CCL5 expression in breast cancer cells." (PMID 37759462, 2023). "CCL5 may be breast-tumor-derived or hematopoietically-derived, which promotes mammary tumor (4T1) progression via generating myeloid-derived suppressor cells (MDSCs) in the bone marrow." (PMID 37759462, 2023). "Furthermore, substantially upregulated long non-coding RNA (lncRNAs), SNHG5, and its downstream signaling molecule, ZNF281CCL2/CCL5, in CAFs play a pivotal role in establishing the premetastatic niche in breast cancer." (PMID 38273859, 2023). "Furthermore, in a recent study with a 4T1 allograft transplantation model, the small GTPase RhoA was shown to function downstream of RKIP and upstream of CCL5 as suppressor of breast cancer lung metastasis." (PMID 36765912, 2023). "Thus, we analyzed the effects of DHEA on breast cancer cell migration as well as of DHEA-treated CM from TNBC cell lines on macrophage recruitment in the presence of CCL5 rh." (PMID 36765778, 2023). "CCL5 levels correlate with advanced breast cancer stage in several studies." (PMID 37759462, 2023). "Furthermore, in gastric cancer, CCL5 levels correlate with tumor progression and prognosis, whereas in breast cancer, CCL5 produced by breast cancer cells increases the production of matrix metalloproteinase by T cells and/or monocytes." (PMID 37987366, 2023). "We conducted a correlation analysis in breast cancer patients to determine whether CCL5 levels are related to clinicopathological features." (PMID 36033472, 2022). "Our previous study found that CCL5 in serum may be positively correlated with lymph node metastasis in breast cancer, but the source of CCL5 in vivo and the reasons for its correlation with lymph node metastasis are still unclear." (PMID 36033472, 2022). "Therefore, this study focused on the receptors and pathways related to the CCL5 protein to study the role and possible mechanism of CCL5 in the metastasis of breast cancer." (PMID 36033472, 2022). "However, CCL5 levels in tumor tissue were higher in breast cancer patients with ER-negative (P = 0.034) or PR-negative (P = 0.009) tumors, a higher nuclear grade (P = 0.013) and a later clinical stage (P < 0.001)." (PMID 36033472, 2022).
breast cancer (continued). "Our study suggests that cryo–thermal therapy combined with targeting CCL5 can desirably reverse immunosuppression and elicit stronger host anti-tumor immunity, leading to improved cryo–thermal therapeutic efficacy against poorly immunogenic breast cancer." (PMID 35327361, 2022). "In other words, CCL5 is positively correlated with clinicopathological features of breast cancer that predict poor prognosis and may also affect disease progression in breast cancer patients as a factor of poor prognosis in breast cancer." (PMID 36033472, 2022). "The expression levels of CCL5 in the serum and tumor tissue of breast cancer patients were detected with a Luminex protein detection kit, and it was found that the expression of CCL5 in serum was positively correlated with the number of axillary lymph node metastases in breast cancer patients." (PMID 36033472, 2022). "In breast cancer, M2 TAMs can directly influence the behavior of tumor cells, whereby TAMs, under the influence of lactate, express and release CCL5 protein via NOTCH, which binds to its receptor in breast cancer cells and induces glycolysis and their epithelial–mesenchymal transition." (PMID 35053485, 2022). "Additionally, in vitro experiments confirmed that breast cancer cells with high expression of CCL5 had weaker proliferation, invasion and metastasis abilities as well as stronger apoptosis and cell cycle arrest abilities." (PMID 36090993, 2022). "CCL5 secreted by TAFs can interact with the CCR5 receptor to promote breast cancer metastasis." (PMID 35982904, 2022). "Notably, there are similarities compared to the role of CCL5 in breast cancer, whose cancer cells can stimulate MSCs to secrete CCL5, and in turn CCL5 promotes cancer cell invasion and metastasis." (PMID 36387070, 2022). "Previous studies demonstrate that PKM2 could interact with p65/NF-κB and affect the expression of downstream target genes in breast cancer and hypoxic pancreatic tumors, while CCL5 was proved to be a downstream target gene of the NF-κB pathway." (PMID 36514094, 2022). "Interestingly, biology research is unusually unified in describing CCL5 as a pro-oncogenic factor, especially in breast cancer." (PMID 36430633, 2022). "Based on the results of the previous analysis, we speculate that CCL5 may be an important factor affecting axillary lymph node metastasis and prognosis in patients with breast cancer." (PMID 36033472, 2022). "In the KEGG and GO enrichment analyses in this study, we found that CCL5 may affect the progression of breast cancer through T-cell-related immune pathways." (PMID 36033472, 2022). "CCL5/CCR5 combination is known for initiating and facilitating inflammatory responses, and acts as a tumor-promoting factor that is tightly associated with the invasive and metastatic stages of breast cancer." (PMID 35701840, 2022). "Considering its strong correlation with the pathogenesis of luminal and HER-2 enriched breast cancer, CCL5 might be used as a potential biomarker for breast cancer screening and risk stratification." (PMID 36685922, 2022). "The combination of cryo–thermal therapy and CCL5 blockades might extend the survival rates of patients with aggressive breast cancer." (PMID 35327361, 2022). "Our results suggested that the combined targeted inhibition of CCL5 could amplify the anti-tumor immunity induced by cryo–thermal therapy and have strong therapeutic impacts on 4T1 murine breast cancer." (PMID 35327361, 2022). "The secretion of the chemokine CCL5/RANTES (Regulated upon Activation, Normal T Cell Expressed and Presumably Secreted) from MSCs is increased by breast cancer cells, which then enhances in turn their motility and dissemination through the chemokine receptor CCR5." (PMID 35150338, 2022). "The addition of low doses of adjuvant RT in breast cancer could be a promising therapeutical tool to reduce collagen VI and maybe impact CCL5." (PMID 36430633, 2022).